PTPRN2 (protein tyrosine phosphatase receptor type N2)
Diseases named in the same sentence as PTPRN2 in open-access papers (continued):
Sharing a sentence is not in itself a finding about the gene and the disease.
steatosis (1 paper, 2023). Increased lipid within the cytoplasm of cells. "We identified dmCpGs in three genes (ANK1, MIR10A, PTPRN2) that were associated with steatosis score." (PMID 36737504, 2023).
viral infections (1 paper, 2021). "Neutrophil activation derived autoantigens (MPO, PRTN3, and PADI4) were prominently increased in blood of both SARS-CoV-1 and SARS-CoV-2 viral infections, while TSHR and PTPRN2 autoantigens were specifically increased in SARS-CoV-2." (PMID 34276672, 2021).
cancer (26 papers, 2005 to 2025). A tumor composed of atypical neoplastic, often pleomorphic cells that invade other tissues. "PTPRN2 encodes a tyrosine phosphatase-like protein whose immature isoform, proPTPRN2 has been overexpressed in human cancers." (PMID 31639042, 2019). "PTPRN2 belongs to the protein tyrosine phosphatase family and is involved in cell migration and cancer metastasis." (PMID 39816677, 2025). "For reference, the most prevalent non-cancer genes were PTPRN2 and DKK1, which were found in five and four cancer types, respectively." (PMID 37558831, 2023). "Although we did not further examine the function of the target gene PTPRN2, limited and contradictory literature is currently reported regarding PTPRN2's involvement in cancer." (PMID 36650953, 2023). "Among the genes in the ZNF132 node, CBX7 is implicated in cancer progression and EMT, PTPRN2 confers resistance to apoptosis, and NTRK3 is a receptor tyrosine kinase whose overactive kinase domain is implicated in growth and metastasis." (PMID 34797887, 2021). "Yet, the mapped genes were highly relevant to PCa etiology and included known cancer drivers LDLRAD4, GMNN, COL1A1, CD38, PTPRN2, GTSE1 and CAMK2N1 in the risk signature and KLK2, AR, KLK3, SPDEF in the relapse signature." (PMID 33845808, 2021). "Some alterations in the genome such as FAM86B1 or GOLGA8A and duplication in the intron of PTPRN2 were up to three times more frequent in our cancer cases than in controls." (PMID 32577795, 2020). "Whereas the tumor suppressive impact of PTEN’s phospholipid phosphatase activity is beyond doubt, only limited and contradicting data exist regarding PTPRN2 involvement in cancer." (PMID 27586084, 2016). "The cancer‐promoting effect of HOXD13 in the colon is partly achieved through PTPRN2." (PMID 34272834, 2021). "Additionally, considerable new information has accumulated over the last few years on the role of the PTPRN2 in the epigenetic regulation of metabolic diseases, neurodegeneration, and cancers." (PMID 35052758, 2021). "PTPRN2, involved in processes ranging from insulin secretion to metastasis and cell migration, is widely reported to be aberrantly methylated in cancer and non-cancer conditions." (PMID 33461589, 2021). "PTPRN2 plays an important role in epigenetic regulation of metabolic diseases and cancers." (PMID 30890718, 2019). "Interestingly, we find that both PTPRN2 and PLCβ1 localize to the plasma membrane, and demonstrate prominent localization to one edge of the plasma membrane, presumably corresponding the leading edge of the cancer cell (Fig EV3A)." (PMID 26620550, 2016). "WIPI2, COL4A2, HDAC4, CUGBP2, PTPRN2 and RUNX2 are Top 6 differential methylation genes, and all of them were reported to take part in regulation of cancers." (PMID 36817452, 2023). "Risk signature contigs mapped at least five other genes with established driver roles in PCa or other cancers: CAMK2N1, COL1A1, GTSE1 and PTPRN2, supporting the relevance of these sequence contigs in PCa etiology." (PMID 33845808, 2021). "This is the first report of methylation in any cancer for five loci (CPVL, HOXC9, PAX8, PTPRN2, and SLC38A4), flagging these loci as potential novel cancer markers." (PMID 18616821, 2008). "No previous reports of methylation of PTPRN2 exist, making it a potentially novel cancer biomarker." (PMID 18616821, 2008). "However, other predicted targets such as SOCS3, PTPRN2, MMP3, PRG1 and BASP1 have not yet been experimentally validated but could be of particular interest on cancer research." (PMID 28346474, 2017).
tumor (20 papers, 2008 to 2025). "Kaplan–Meier analysis and Cox proportional hazard models showed that low expression of all the candidate genes except for PTPRN2 were associated with tumor progression and recurrence in a PCa cohort." (PMID 31221986, 2019). "We found that low expressed genes (except PTPRN2) were associated with worse DFS as indicated by the presence of biochemical recurrence (rising PSA levels following local therapy) or radiological tumor recurrence/metastasis." (PMID 31221986, 2019). "The encoded protein PTPRN2 is a tumor-suppressor gene involved in malignant cell transformation." (PMID 41226303, 2025). "PTPRN2 gene is epigenetically regulated in various biological processes including tumor pathogenesis." (PMID 30890718, 2019). "PTPRN2_AS1 can adsorb miR-145-5p through the ceRNA mechanism, thereby relieving its inhibition on PTPRN2 and enhancing the activity of the insulin signaling pathway, promoting tumor cell glycolysis, which also crucial in the energy metabolism reprogramming of OSCC." (PMID 41287790, 2025). "However, PTPRN2 showed a positive correlation with tumor purity, suggesting relatively higher expression in the tumor." (PMID 41132793, 2025). "PTPRN2, a gene involved in insulin secretion, and MAD1L1, which plays a role in the cell cycle and tumor suppression, contained DMRs in males and females in both cohorts." (PMID 35500004, 2022). "There were more poor prognostic deletions in the tumor characterization functional category (e.g., MUC4 and PTPRN2 gene deletions) and better prognostic deletions in the lymphocyte regulation functional category." (PMID 33431054, 2021). "Lastly, we observed an inverse relationship between the expression of PTPRN2, LAT and SLC39A5 genes and HR of tumour recurrence from the TCGA PRAD dataset." (PMID 31221986, 2019). "PTPRN2, an EMT-related (epithelial-mesenchymal transition) gene, is significantly higher in circulating tumor cells of CRPC patients than those of castration-sensitive patients." (PMID 31221986, 2019). "Of these, eight showed highly significant hypermethylation in tumor tissue (p < 0.0001): GDNF, MTHFR, OPCML, TNFRSF25, TCF21, PAX8, PTPRN2 and PITX2." (PMID 18616821, 2008). "A heatmap of the 110 CpGs shows overall lower methylation of these CpGs in tumors compared to adjacent non-tumor tissues: the top five hypermethylated genes were GLRX, WNT9B, SEPT9, KIAA00284, and PPYR1, and the top five hypomethylated genes were KIAA0748, PAEP, PCDH15, PTPRN2, and DUSP27." (PMID 34635168, 2021).
cardiovascular disease (2 papers, 2017 to 2021). "Seven of these DMPs (25%) could be allocated to a gene that was previously associated with cardiovascular diseases (HDAC4, IGF2BP3, CASZ1, SDK1, PCDHGA1, DIO3, PTPRN2)." (PMID 34895303, 2021).
neurodevelopmental disorder (2 papers, 2019 to 2022). A behavioral and cognitive disorder with onset during the developmental period that involves impaired or aberrant development of intellectual, motor, or social functions. "PTPRN2, MAD1L1, and AGAP1 are all linked to neurodevelopmental disorders and associate significantly with PAE or FASD in two or more previous genome-wide DNAm studies." (PMID 36581877, 2022).
neurological disease (2 papers, 2020). "The genes that contained most VNTRs, of which PTPRN2 and DLGAP2 are the most prominent examples, were found to be predominantly expressed in the brain and associated with a wide variety of neurological disorders." (PMID 33139705, 2020).
adenocarcinoma (1 paper, 2011). A common cancer characterized by the presence of malignant glandular cells. "PTPRN2 also showed significantly increased DNA methylation from AIS to adenocarcinoma." (PMID 21731750, 2011). "PTPRN2 showed a further significant increase in DNA methylation in adenocarcinoma vs. AIS (the increase from AAH to AIS did not meet our multiple comparisons threshold)." (PMID 21731750, 2011).
cardiac disease (1 paper, 2023). "Most frequently reported were TEAD1 (TEA Domain Transcription Factor 1) and PTPRN2 (Protein Tyrosine Phosphatase Receptor Type N2) in association with outcomes ranging from vascular to cardiac disease." (PMID 36991458, 2023). "Both genes were mentioned in association with a variety of outcome events ranging from vascular to cardiac disease with PTPRN2 being a predisposing factor for cardiac disease." (PMID 36991458, 2023).
PTPRN2 also shares sentences with these, for which no sentence is quoted: metabolic disease (4 papers); bipolar disorder (2); cocaine addiction (2); Graves disease (2); Hashimoto thyroiditis (2); male infertility (2); metabolic syndrome (2); Parkinson disease (2); Alpha-thalassemia (1); Alzheimer disease (1); anxiety disorder (1); attention deficit-hyperactivity disorder (1); autism (1); autoimmune thyroid disease (1); brain disorder (1); chronical obstruction pulmonary disease (1); cognitive decline (1); Cognitive impairment (1); dementia (1); Down syndrome (1); Epstein-Barr virus infection (1); Glucose intolerance (1); hepatic disease (1); hepatocellular carcinoma (1); Huntington disease (1); hyperandrogenism (1); Hypoglycemia (1); infection (1); learning disorder (1); leiomyoma (1).
A further 16 diseases each share a sentence with PTPRN2 in 1 paper.